NRF1 (nuclear respiratory factor 1)
Diseases named in the same sentence as NRF1 in open-access papers (continued):
Sharing a sentence is not in itself a finding about the gene and the disease.
melanoma (8 papers, 2014 to 2024). A malignant, usually aggressive tumor composed of atypical, neoplastic melanocytes. "Although the current study addresses for the first time the association of NRF1 in melanoma, its retrospective nature causes also some weaknesses." (PMID 31687076, 2019). "We also observed that the NRF1 mRNA level decreased from benign naevi to dysplastic naevi and to melanomas and that their levels associate with ulceration." (PMID 31687076, 2019). "Whether ERK signalling causes these changes in NRF-1 in melanoma cells remains to be determined." (PMID 29050218, 2017). "In summary, these findings indicate that CD47 transcriptional regulation by NRF-1 is determined by the proximal promoter region in melanoma cells." (PMID 39742254, 2024). "Our results support the concept that reduced autophagic activity contributes to melanoma development and progression, and identifies NRF1 as a novel TF involved in the regulation of both ATG5 and ATG7 genes." (PMID 34458153, 2021). "Since our previously published and current data show decreased expression of three of the core ATGs (ATG5, ATG7 and Beclin-1) in melanoma, we decided to study the impact of NRF1 and NFE2L2 on the expression of these ATGs." (PMID 34458153, 2021). "The immunohistochemical expression of nuclear NRF1 decreased from benign to dysplastic naevi (p < 0.001) and to primary melanoma (p < 0.001) and from primary melanoma to metastatic lesions (p = 0.012)." (PMID 31687076, 2019). "Although the level of NRF1 mRNA decreased nearly significantly between primary melanomas and metastases (p = 0.053), the difference in NRF2 mRNA levels was not significant between primary melanomas and metastases." (PMID 31687076, 2019). "Very early on in melanoma carcinogenesis, both NRF1 and NRF2 were found to be downregulated at the protein level as well as at the mRNA level." (PMID 31687076, 2019). "We also studied the expression of some redoximiRNAs from the same sample set and described some new data on their expression level changes in melanoma carcinogenesis and correlation with immunohistochemical and mRNA expression levels of NRF1 and NRF2." (PMID 31687076, 2019). "In immunohistochemistry, the protein level of NRF1 had a decreasing trend during melanoma carcinogenesis." (PMID 31687076, 2019). "Taken together, these results demonstrate that NRF-1 is responsible for BRAF/MEK-mediated regulation of CD47 expression in melanoma cells." (PMID 29050218, 2017). "Here we report that oncogenic activation of ERK plays an important role in transcriptional activation of CD47 through nuclear respiratory factor 1 (NRF-1) in melanoma cells." (PMID 29050218, 2017). "We monitored the expression of NRF-1 in melanoma cells in response to treatment with BRAF and MEK inhibitors." (PMID 29050218, 2017). "Importantly, downregulation of NRF1 causes notable reduction of CD47 mRNA (>50%) and as a result, significant decrease in melanoma cell poolations with high CD47 levels." (PMID 39742254, 2024). "It is unlikely that NRF1 is the sole driver of autophagy and melanoma progression in patients." (PMID 34458153, 2021). "Therefore, it is possible that decreased NRF1 activity and consequently expression of ATGs is the result of decreased PGC1α levels and/or PGC1α activity in melanomas." (PMID 34458153, 2021). "Indeed, we observed that knockdown of NRF1 leads to an increased migration potential in melanoma cells." (PMID 34458153, 2021). "This phenomena could be explained by altered NRF1 activity in melanoma patients, impact of other TFs on ATG gene expression or the involvement of post-transcriptional regulation." (PMID 34458153, 2021). "The other study indicated that Nrf1 was involved in the melanoma carcinogenesis." (PMID 33413440, 2021).
melanoma (continued). "Despite the contradictory result in the expression trends, current p40-NRF2 results support our previous observation, namely, that the NRF2 expression favours worse disease-specific survival, and the role of NRF2 in melanoma carcinogenesis seems to be rather consistent with NRF1." (PMID 31687076, 2019). "The expression of both NRF1 antibodies showed a significant NRF1 decrease from benign to dysplastic naevi (p < 0.001 and p = 0.034, Supplementary) and from naevi to primary melanoma, as well as to metastatic lesions (p < 0.001)." (PMID 31687076, 2019). "Our results now suggest that NRF-1 may play a part in protection of melanoma cells from the immune system through CD47." (PMID 29050218, 2017). "Furthermore, we found that knockdown of NRF1 increases the migration potential of melanoma cells." (PMID 34458153, 2021). "Therefore, ERK activation upregulates NRF-1 in melanoma cells." (PMID 29050218, 2017). "So these results suggest that NRF-1-mediated regulation of CD47 expression is a novel mechanism by which ERK signalling promotes the pathogenesis of melanoma, and that the combination of CD47 blockade and BRAF/MEK inhibitors may be a useful approach for improving their therapeutic efficacy." (PMID 29050218, 2017). "Thus, because glucocorticoids increase ROS generation in metastatic B16 melanoma cells, we investigated whether the decrease in γ-GCS activity in iB16-shGCR metastatic cells is associated with changes in nuclear Nrf1 and/or Nrf2." (PMID 24802641, 2014). "In order to evaluate endogenous NRF-1 activity at the CD47 promoter, we generated melanoma cell lines to stably express all versions of Luc reporters using previously published lentiviral transduction protocols." (PMID 39742254, 2024). "Next, to determine NRF-1 regulation of CD47 promoter, we performed Chromatin Immunoprecipitation (ChIP) assays on malignant patient-derived melanoma cells, as well as, adult normal melanocytes and HepG2 cells." (PMID 39742254, 2024). "Taken together, we identified NRF1 as a novel TF involved in the regulation of ATG5 and ATG7 in melanoma and therefore provide novel insights into the transcriptional regulation of autophagy." (PMID 34458153, 2021). "In addition, the decline in NRF1 and NRF2 mRNA levels from benign naevi to melanomas could be reproduced when comparing the NRF1 and NRF2 mRNA levels in cell culture lysates in the qPCR, showing a decrease of relative mRNA levels between benign melanocyte and malignant melanoma cells." (PMID 31687076, 2019). "In summary, we have shown in this study that treatment with BRAF/MEK inhibitors upregulates CD47 expression through NRF-1, and that this is mediated by reactivation of ERK in melanoma cells." (PMID 29050218, 2017). "Another important finding of this study is that NRF-1 is responsible for ERK-mediated constitutive expression of CD47 and its upregulation upon BRAF/MEK inhibitor treatment in melanoma cells." (PMID 29050218, 2017). "Immunohistochemical expression of NRF3 was then studied in a sample set of benign and dysplastic naevi, melanomas, and their lymph node metastases showing that similar to NRF2 and NRF1, NRF3 was also downregulated during melanoma carcinogenesis at the protein level." (PMID 35378827, 2022). "We performed a siRNA-mediated knockdown of NRF1 and NFE2L2 in melanoma cells." (PMID 34458153, 2021). "To investigate whether there is a connection between the expression of NRF1, NFE2L2 and ATGs, we analysed existing microarray data and investigated the gene expression profiles of 18 benign nevi and 45 primary melanoma tissue samples." (PMID 34458153, 2021). "Therefore, we decided to further investigate NRF1-mediated transcriptional regulation of ATG7 and ATG5 genes in melanoma cells." (PMID 34458153, 2021). "Furthermore, we identified NRF1 as a new transcription factor involved in the regulation of ATG5 and ATG7, improving our current understanding of the regulation of autophagy during melanoma development and progression." (PMID 34458153, 2021).
melanoma (continued). "The immunohistochemical expressions of NRF1 and p40-NRF2 did not associate with the melanoma patients' age, gender, lesion location, Breslow's thickness, ulceration, mitotic activity, or pigmentation." (PMID 31687076, 2019). "However, NRF1 and NRF2 mRNA correlated with melanoma patients' gender (higher mRNA levels in males, p = 0.037 and p = 0.017, n = 20 and n = 19, respectively), and NRF1 mRNA also correlated positively with the presence of ulceration (p = 0.016, n = 18)." (PMID 31687076, 2019). "On the other hand, silencing of NRF1 could, in addition to the expression of ATG5 and ATG7, target several other genes, which could positively or negatively influence the migration potential of melanoma cells." (PMID 34458153, 2021). "In addition, NRF1 and NRF2 mRNA and miR-23B, miR-93, miR-144, miR-212, miR-340, miR-383, and miR-510 levels were analysed with real-time qPCR from 54 paraffin-embedded naevi and melanoma samples." (PMID 31687076, 2019). "Nuclear NRF1 expression, which predicted exceptionally poor melanoma-specific outcome in those patients without nodal metastases at the time of diagnosis, might benefit the carcinogenetic process by alleviating oxidative and ER stress accumulated in the aggressive disease." (PMID 31687076, 2019). "Although miR-93-5p, miR-144, and miR-212 had a predicted relation with NRF1 and NRF2, apparently, this is not the case in melanoma and the lack of correlation may reflect the general discoordination within a cancer cell." (PMID 31687076, 2019).
multiple myeloma (8 papers, 2014 to 2024). "The DDI2-dependent NRF1 pathway has been mostly proposed to contribute to susceptibility and resistance to treatments with proteasome inhibitors in multiple myeloma." (PMID 37720101, 2023). "Furthermore, inhibition of NRF1 activation has been shown to increases the susceptibility of Multiple Myeloma to proteasome inhibitor-based chemotherapy." (PMID 37720101, 2023). "In cancer therapies that utilize proteasome inhibitors (e.g., multiple myeloma), there is now a stronger justification to inhibit the Nrf1 pathway to increase the treatment efficacy." (PMID 38656405, 2024). "In contrast, it is also conceivable that NRF1 activation may confer resistance to bortezomib, a proteasome inhibitor commonly utilized in the treatment of multiple myeloma." (PMID 37658135, 2023). "Furthermore, we found that in response to BTZ, the myeloma cells tested showed variability of sensitivity and diverse patterns of NRF1 maturation." (PMID 35589686, 2022). "It will be interesting to see whether blockade of the Nrf1-mediated bounce-back response through inhibition of p97 enhances the efficacy of proteasome inhibitor therapy in multiple myeloma or enables expansion of proteasome inhibitor therapy into new indications." (PMID 24448410, 2014).
lung cancer (7 papers, 2010 to 2025). A malignant neoplasm involving the lung. "For instance, overexpression of PD‐L1 induced by the aryl hydrocarbon receptor in non–small cell lung cancer reduces the efficacy of anti‐PD‐1 treatment; IL‐17A increases PD‐L1 expression via the p65/NRF1/miR‐15b‐5p axis, promoting resistance of CRC to PD‐1 antibody therapy." (PMID 39503247, 2024). "Furthermore, the binding of nuclear respiratory factor 1 to the nuclear respiratory factor‐binding element located 50‐bp upstream of its transcription start site was important for VSNL1 expression in non‐small cell lung cancers." (PMID 37096864, 2023). "This novel observation suggests that reduced levels of MAFG and higher levels of NRF1 (negative regulator) may be suppressing the transcription of these ARE-regulated genes among smokers who go on to develop lung cancer." (PMID 20689807, 2010). "Inter and intra-patient heterogenous NQO1 expression was observed in lung cancer, displaying NQO1 expression are independent of NRF1 and NRF2 in tumors." (PMID 36359002, 2022).
sarcopenia (7 papers, 2019 to 2026). Progressive decline in muscle mass due to aging which results in decreased functional capacity of muscles. "Collectively, functional decline of the SIRT1–PGC-1α–NRF1/2–TFAM axis constitutes a central event underlying mitochondrial biogenic failure in sarcopenia and represents a promising therapeutic target." (PMID 41568005, 2025). "Mechanistically, this associates with the downregulation of an ERRα/PGC-1α/NRF1 regulatory module, lower NAD+ levels and alterations of mitochondrial respiratory complex protein expression and activity in human sarcopenia." (PMID 31862890, 2019). "In senescence-accelerated mouse prone-8 (SAMP8) mice, a well-studied murine model for age-related disease exhibiting typical features of skeletal muscle senescence, downregulation of Pgc-1α, Nrf-1, and Tfam during the onset and development of sarcopenia was observed." (PMID 37299588, 2023). "At the molecular level, mitochondrial alterations in sarcopenia involve the perturbation of a transcriptional module with reduced expression or activity in sarcopenic muscle of the transcriptional regulators ERRα and NRF1 and their coactivator PGC-1α." (PMID 31862890, 2019). "NRF2 knockout exacerbated frailty and sarcopenia of mice during aging, accompanied by the reduced expression levels of PGC-1α, NRF1, and TFAM, as well as a reduction of mitochondrial content in the skeletal muscle." (PMID 37152937, 2023). "The expression levels of PGC-1α, NRF1, and TFAM are decreased in the skeletal muscle of senescence-accelerated mouse (SAM) prone 8 (SAMP8) during the onset and development of sarcopenia." (PMID 37152937, 2023). "NRF-1, TFAM and mtDNA represent the dysregulation of mitochondrial quality control processes and contribute to sarcopenia." (PMID 35631191, 2022). "PGC-1α, Nrf-1 and Tfam are downregulated in SAMP8 mice during the onset and development of sarcopenia." (PMID 34881083, 2021). "Given the potential for NRF1 to serve as a sensor responding to the lipid component in the bilayer lipid membrane and the potential regulatory role of docosahexaenoic acid (DHA, C22:6, n-3) in proteasome activity in sarcopenia, we considered DHA a natural regulator of NRF1." (PMID 41545342, 2026). "Intriguingly, HtrA2 apparently regulates mitochondrial biogenesis in sarcopenia via the differential expression of Nrf-1/2, but not PGC-1α." (PMID 34881083, 2021). "Moreover, individuals with sarcopenia exhibited reduced expression levels of Pgc-1α, ERRα, and other coactivators, such as Nrf-1 and Nrf-2, compared with those in individuals without sarcopenia." (PMID 37299588, 2023). "Interestingly, perturbed NRF1 signaling was only detected through the transcriptional downregulation of its direct target genes, but its expression level was not affected by sarcopenia." (PMID 31862890, 2019).
depression (6 papers, 2024 to 2025). "Upregulated NRF1 is associated with ameliorated depressive-like behaviors and improved cognitive dysfunctions in electroacupuncture-treated mice with post-stroke depression." (PMID 38773376, 2024). "Taken together, these results suggest that hippocampal SIRT1 mediates the ameliorative effect of exercise on anxiety- and depression-like behaviors in APP/PS1 mice through the PGC-1α/NRF1/TFAM/mitochondrial biogenesis pathway." (PMID 39744519, 2024). "Additionally, a study in an animal model of depression induced by prenatal stress found that the reduced level of PGC-1α protein in the hippocampus inhibits mitochondrial biogenesis through the PGC-1α/NRF1/TFAM pathway, leading to depressive-like behavior." (PMID 40699781, 2025). "Additionally, electroacupuncture therapy has been found to successfully improve depression-like behaviour and cognitive dysfunction while inducing the Nrf1/TFAM pathway after I/R injury." (PMID 39198723, 2024). "IGF-1 can activate the CREB/PGC-1α signaling pathway to regulate the expression of genes such as NRF1, TFAM, and the mitochondrial dynamics-related protein Drp1, promoting mitochondrial biogenesis and improving function, ultimately alleviating depression." (PMID 40699781, 2025). "In total, hippocampal SIRT1 regulates the SIRT1/PGC-1α/NRF1/TFAM/mitochondria biogenesis axis to mediate the ameliorative effect of treadmill exercise on anxiety- and depression-like behaviors in APP/PS1 mice." (PMID 39744519, 2024). "Therefore, the SIRT1-dependent PGC-1α/NRF1/TFAM signaling pathway, which mediates mitochondrial biogenesis, plays a significant role in the intervention of anxiety and depression-like behaviors." (PMID 39744519, 2024). "Finally, we investigated the effects of pharmacological activation of SIRT1 on anxiety- and depression-like behaviors, the SIRT1/PGC-1α/NRF1/TFAM signaling axis, and mitochondrial biogenesis." (PMID 39744519, 2024). "Activated PGC-1α cooperates with NRF1/2 to upregulate TFAM expression, promoting the replication of mitochondrial DNA (mtDNA) and protein synthesis through the PGC-1α-NRF1/2-TFAM pathway, ultimately facilitating mitochondrial biogenesis and alleviating depression." (PMID 40699781, 2025).
Huntington disease (6 papers, 2011 to 2023). Huntington disease (HD) is a rare neurodegenerative disorder of the central nervous system characterized by unwanted choreatic movements, behavioral and psychiatric disturbances and dementia. "TAF4, a NRF1 target gene, is associated with Huntington’s disease." (PMID 27983596, 2016). "This becomes apparent in the fact that the PGC-1α-NRF-1/2-TFAM pathway is downregulated in many neurodegenerative diseases including Parkinson’s disease (PD), Huntington’s disease (HD) and Alzheimer’s disease (AD)." (PMID 36358945, 2022).
lung adenocarcinoma (6 papers, 2012 to 2024). A carcinoma that arises from the lung and is characterized by the presence of malignant glandular epithelial cells. "In KRAS-mutant lung adenocarcinomas, significant activation of NRF1 targets was associated with worse prognosis, consistent with NRF1’s role as a regulator of the proteasome pathway, a key dependency in KRAS-mutant cancers." (PMID 36950380, 2023). "Estradiol has been reported to increase mtDNA content in breast and lung adenocarcinoma cells that directly stimulate NRF-1 gene expression and increase TFAM expression, mitochondrial transcription and oxygen consumption." (PMID 22676897, 2012). "ERR-α and NRF-1/2 have been demonstrated to participate in lung adenocarcinoma progression." (PMID 38242874, 2024). "Therefore, we aimed to address the findings of NQO1 expression across the TME and normal tissue, co-registered with NRF1 and NRF2 in lung adenocarcinoma to expand NRF1 and NRF2 research in NSCLC." (PMID 36359002, 2022). "Others reported that estrogen increases NRF-1 transcription, resulting in a coordinated increase of expression of nuclear- and mitochondrial-encoded genes and mitochondrial respiratory activity in MCF-7 breast and H1793 lung adenocarcinoma cells." (PMID 22952593, 2012).
renal fibrosis (6 papers, 2020 to 2025). A final common manifestation of a wide variety of chronic kidney diseases characterized by glomerulosclerosis and tubulointerstitial fibrosis. "ANGPT2 was identified as a significant mediator of renal fibrosis and autophagy in diabetic nephropathy, whose knockdown increased autophagy level and attenuated renal fibrosis via activating the MEK/ERK/Nrf-1 pathway." (PMID 36272879, 2023). "Previous studies have shown that Nrf1 might act as a novel renal fibrosis antagonist in renal fibroblast cells." (PMID 33505436, 2020). "Supporting this, our previous study demonstrated that SFN activated mitochondrial biogenesis by PGC-1α/NRF1 pathway in the UUO model, reducing renal fibrosis." (PMID 40227243, 2025). "A previous study has shown that ANGPT2 was identified as an important mediator of renal fibrosis and autophagy in diabetic nephropathy, and its knockdown increased autophagy and reduced renal fibrosis by activating the MEK/ERK/Nrf-1 pathway." (PMID 38808888, 2024).